SHH (sonic hedgehog signaling molecule)
Diseases named in the same sentence as SHH in open-access papers (continued):
Sharing a sentence is not in itself a finding about the gene and the disease.
prostate carcinoma (28 papers, 2006 to 2025). A carcinoma that arises from epithelial cells of the prostate gland. "Previous research has linked SHH signaling to prostate cancer progression and resistance to hormone therapy." (PMID 40432836, 2025). "In this study, we have highlighted the role of the Mediator subunit 12 (MED12) in this process as MED12 is frequently mutated in prostate cancer and has previously been linked to regulation of SHH signaling." (PMID 37520466, 2023). "The SHH signaling pathway promotes androgen-independent prostate cancer and causes therapy resistance via increasing ABC transporter levels." (PMID 36969009, 2023). "Bioinformatic and immunohistochemistry analyses revealed that decreased OLFM4 and increased SHH expression was significantly associated with advanced human prostate cancer." (PMID 26581960, 2015). "Loss of protein expression of OLFM4 and increased expression of SHH were significantly associated with high grade of prostate cancer." (PMID 26581960, 2015). "Thus, it is highly feasible that aberrant activation of the SHH signaling pathway is a key player in causing prostate cancer cells to bypass androgen dependence to promote progression towards CRPC." (PMID 37520466, 2023). "Dysregulated GLI3-dependent SHH signaling, as a result of mutant or downregulated MED12, has been shown to play an important role in X-linked disability syndromes and prostate cancer progression." (PMID 38915457, 2024). "Components of the SHH pathway, including GLI1 (GLI family zinc finger 1), PTCH1 (protein patched homolog 1), and SHH, are highly up-regulated in human prostate cancer tissues, compared with prostatic epithelium." (PMID 36969009, 2023). "To inhibit prostate cancer bone metastasis progression, we used SHH siRNA to interfere with the SHH-RANKL-IL6 signaling network between bone stromal cells and cancer cells." (PMID 35285760, 2022). "Actually, the interaction between cancer cells and bone microenvironment plays important role in prostate cancer bone metastasis, especially the Sonic hedgehog protein (SHH) signaling in the bone microenvironment." (PMID 35285760, 2022). "GLI1 is an important component of the SHH (Sonic Hedgehog Signaling Molecule)-GLI signaling pathway that is positively correlated with prostate cancer severity." (PMID 32765970, 2020). "The percentage of OLFM4- and SHH-positive prostate-cancer specimens was 80% and 40% in Gleason scores 4–7, and 22% and 57% in Gleason scores 8–10, respectively." (PMID 26581960, 2015). "The expression of OLFM4 and SHH proteins was examined in prostate-cancer tissue-array samples using immunohistochemistry." (PMID 26581960, 2015). "We showed previously that PN1-uPA complexes preferentially signal through the LRP-1 to control SHH signalling in prostate cancer." (PMID 25686839, 2015). "Early reports exploring the role of inhibiting the pathway via cyclopamine or anti-SHH antibodies suggested a direct role for the Hh pathway in the development and progression of prostate cancer." (PMID 26426053, 2015). "In prostate cancer, the mRNA levels of SHH, PTCH1 and GLI1 were highly elevated in more advanced stages of the cancer, and all those components were closely linked to Gleason score." (PMID 25369201, 2014). "Our group, along with collaborators, demonstrated the association of high levels of Pln protein with 54% of advanced prostate cancer tumors and its role in tumor cell proliferation by regulating SHH signaling." (PMID 22135748, 2011). "Given that Perlecan has been shown to modulate the signaling of multiple growth factors including FGF2, FGF10 and VEGF, we asked if the reduction of prostate cancer cell growth in Perlecan siRNA treated cells was a result of decreased SHH signaling." (PMID 16507112, 2006). "Perlecan forms complexes with increasing amounts of SHH that correlate with increasing metastatic potential of the prostate cancer cell line." (PMID 16507112, 2006).
prostate carcinoma (continued). "Inhibition of Perlecan expression by siRNA in prostate cancer cell lines decreases SHH signaling while expression of the downstream SHH effector GLI1 rescues the proliferation defect." (PMID 16507112, 2006). "Taken together, the results of our expression, inhibition, and biochemical studies link Perlecan expression and function to SHH-GLI pathway activity in advanced prostate cancer cells." (PMID 16507112, 2006). "Here we demonstrate Perlecan expression in prostate cancer, and its function in prostate cancer cell growth through interaction and modulation of Sonic Hedgehog (SHH) signaling." (PMID 16507112, 2006). "In vitro studies have highlighted the combined effect of BMP4 and SHH in supporting the survival of prostate cancer cells and promoting the differentiation of bone stromal cells, which may lead to the osteoblastic metastasis typical of prostate cancer." (PMID 40304052, 2025). "Based on our findings, the use of SHH inhibitors could prove to be beneficial in treating this subset of prostate cancer." (PMID 37520466, 2023). "Therefore, in this study, we have investigated the link between MED12 and GLI3-dependent SHH signaling and how MED12 mutations promote progression of primary prostate cancer towards CRPC." (PMID 37520466, 2023). "Inhibiting the SHH signaling pathways with anti-SHH antibodies diminishes prostate cancer growth." (PMID 36969009, 2023). "Furthermore, knockdown of Mettl3 decreased expression of GLI1, a component of the Sonic hedgehog (SHH) signaling pathway, which prostate cancer cells are dependent on for survival." (PMID 35350378, 2022). "Lian and colleagues firstly proposed the paracirne manner of SHH signaling in stromal cells in prostate cancer, and demonstrated that paracrine SHH signaling could promote tumor growth." (PMID 27039174, 2016). "Melanomas and carcinomas of the prostate have further shown a SHH-Gli signaling axis." (PMID 22087285, 2011). "Interestingly, in the LNCaP-C4-2B cell line series, a well-known model of prostate cancer progression, we have shown that SHH signaling increases with increasing metastatic potential but Pln protein levels do not." (PMID 22135748, 2011). "Finally, we have shown that Perlecan is required for SHH signaling during human prostate cancer growth, which reveals a new system for the investigation of the mechanism of Perlecan action." (PMID 17980035, 2007). "We propose that Perlecan may sustain the growth of nutrient starved prostate cancer cells in rapidly spreading tumors by amplifying their sensitivity and response to SHH signaling." (PMID 16507112, 2006). "In vitro investigations have illuminated the cooperative impact of BMP4 and SHH on fostering the survival of prostate cancer cells alongside the differentiation of bone stromal cells, potentially culminating in the osteoblastic metastasis characteristic of prostate cancer." (PMID 38049682, 2023). "Due to prostate cancer cells’ dependence on SHH signaling, decreased expression of GLI1 deprived prostate cancer cells of SHH signaling and forced apoptosis." (PMID 35350378, 2022). "We found that expression of the hedgehog-signaling components SHH, PTCH1, and GLI1 was reduced between 30–70% in OLFM4-expressing prostate-cancer cells compared with control vector-transfected cells." (PMID 26581960, 2015). "Protein expression of the hedgehog signaling-pathway components SHH, PTCH1, GLI1, and GLI2 was also generally reduced in OLFM4-expressing prostate-cancer cells compared with control vector-transfected cells." (PMID 26581960, 2015). "Given our results observed in Olfm4-knockout mice and human prostate-cancer cells, we sought to analyze the expression of OLFM4, SHH, and hedgehog signaling-pathway target genes in the GSE3598819 and GDS2545 (GEO profiles) datasets." (PMID 26581960, 2015).
prostate carcinoma (continued). "At first sight, the role of Serpine2/PN-1 appears at odds with its established role in inhibiting SHH signaling and GNP proliferation during cerebellar development and its recently demonstrated functions in reducing proliferation of metastatic prostate cancer cells." (PMID 25901736, 2015). "These authors show that MMP-9 promotes SHH signaling and tumor growth indirectly by cleaving SERPINE2/PN-1 and propose that increasing its levels may be critical for blocking malignant progression of prostate cancer." (PMID 25901736, 2015). "In addition, AR-positive, androgen-sensitive VCaP prostate-cancer cells transiently overexpressing OLFM4 displayed reduced expression of SHH and GLI at the mRNA level but not the protein level." (PMID 26581960, 2015). "METTL3 positively regulates prostate cancer cell proliferation and metastasis through GLI1 rather than other components of the SHH cascade in an m6A modification-dependent manner, while the underlying mechanism remains to be investigated further." (PMID 37149646, 2023). "We detected positive OLFM4 staining, but not SHH staining, in Gleason score 4–7 prostate-cancer specimens, while OLFM4 staining was reduced or lost and SHH staining was increased in Gleason scores 8–10 prostate-cancer specimens." (PMID 26581960, 2015).
glioblastoma (27 papers, 2011 to 2025). The most malignant astrocytic tumor (WHO grade IV). "In glioblastomas, the abnormal activation of SHH signaling typically by mutation in Patched1 and/or activating mutations in SMO leads to the transformation of adult stem cells into glioblastoma stem cells." (PMID 32290213, 2020). "Sonic Hedgehog (SHH)-Gli signalling pathway regulates self-renewal and tumourigenic potential of GCSCs and active SHH signalling has been associated with glioblastoma." (PMID 23998913, 2013). "Therefore, SHH signaling has become one of the focal points for glioblastoma treatment since mutations in the pathway play a key role in cell proliferation and tumorigenesis." (PMID 32290213, 2020). "HES1, a downstream target of Notch signalling, modulates SHH signalling in glioblastoma by binding to N-boxes within GLI1's first intron, suppressing its expression and potentially inhibiting the HH cascade." (PMID 39568072, 2024). "Hedgehog (SHh) signal endows tumors with high invasiveness, and its aberrant activation drives tumorigenesis in various cancers, including glioblastoma." (PMID 37533228, 2023). "It is interested that ID1 regulates Wnt and SHH signaling in glioblastoma stem cells by suppressing CULLIN3 ubiquitin ligase." (PMID 33834612, 2021). "Upregulating the expression levels of Notch1 and SHH likely contributed to the effect exerted by β-elemene on glioblastoma cell differentiation." (PMID 26563263, 2015). "Binding of SHH-N to PTCH1 in the embryonic neural tube results in release of PTCH1-regulated inhibition of Smoothened (SMO) and regulation of the expression of SHH target-genes, like the glioblastoma (Gli) protein family members, Gli1, Gli2, and Gli3." (PMID 24865218, 2014). "Therefore, the combination of miR-326 and curcumin presents a promising strategy for glioblastoma treatment by increasing glioma cell chemosensitivity to curcumin, primarily through SHH/GLI1 pathway inhibition." (PMID 40227413, 2025). "Additionally, the expression of sonic hedgehog (SHH) signaling-related proteins (SHH, smoothened homolog (Smo) and glioblastoma (Gli)) and CUL3 was tested with western blotting." (PMID 35715796, 2022). "This pathway plays a major role in developmental processes and several studies have demonstrated that the activation of the SHH signaling pathway induces migration of various cell types including glioblastoma, liver cancer cells, fibroblasts, endothelial cells, monocytes as well as aortic SMCs." (PMID 31649532, 2019). "The transcriptomics data on 149 clinical cases of The Cancer Genome Atlas-Glioblastoma database showed a strong correlation between PTCH1 and GLI1 upregulated expression in GBM indicating that activation of the canonical SHH pathway might be associated with this malignancy." (PMID 36010607, 2022). "In addition, Sonic Hedgehog homolog (SHH), which mediates molecular signals to the embryonic cells required for normal development and Notch, plays a crucial role as an important factor influencing neural progenitor behavior and is dysregulated in glioblastoma stem cells (GSCs)." (PMID 36627893, 2022). "MiR-302-367 cell-to-cell transfer decreases the expression levels of CXCR4/SDF1, SHH, cyclin D, cyclin A, and E2F1 to inhibit glioblastoma growth." (PMID 34113619, 2021). "Glioblastoma Multiforme (GBM), the most common and lethal adult primary tumor of the brain, showed a link between Sonic Hedgehog (SHH) pathway in the resistance to temozolomide (TMZ)." (PMID 25595896, 2015). "Hh signaling appears to be active in glioblastoma multiforme (GBM)-derived neurospheres and glioma stem cell cultures (gliomaspheres), as they express GLI1, PTCH1, SMO and SHH." (PMID 26270676, 2015). "Previous studies have showed that increasing ARL13B in glioblastoma cells promoted ciliary SMO accumulation, independent of exogenous SHH addition." (PMID 37830570, 2023).
lung carcinoma (26 papers, 2007 to 2025). "For example, SFN has been shown to curb the growth of gefitinib-resistant lung cancer cells by altering the sonic hedgehog (SHH) signaling pathway and reducing the expression of markers associated with lung cancer stem cells." (PMID 38919393, 2024). "We demonstrated that miR-506-3p underexpression is associated with increased expression of SHH and is associated with increased invasiveness and EMT phenotype of lung cancer cells through the induction of the SHH signaling pathway." (PMID 33291316, 2020). "Our results advanced our understanding of the molecular mechanisms underlying EGFR-TKI resistance and indicated that the miR-506/SHH axis might represent a novel therapeutic target for future EGFR mutated lung cancer treatment." (PMID 33291316, 2020). "Through the SHH signaling system, combination therapy with sulforaphane and gefitinib dose-dependently decreases the growth of gefitinib-resistant lung cancer cells and inhibits the expression of SHH, SMO, and GLI1." (PMID 40728967, 2025). "The SHH cascade was upregulated in stem spheres and chemo-resistant lung cancer cells and was accountable for drug resistance against multiple chemotherapy regimens." (PMID 37149646, 2023). "Combination treatment with sulforaphane and gefitinib dose-dependently inhibits the expression of SHH, SMO, and GLI1 and suppresses the proliferation of gefitinib-resistant lung cancer cells through the SHH signaling pathway." (PMID 36770689, 2023). "The sonic hedgehog (SHH) cascade and its key terminal factor, glioma-associated oncogene homolog 1 (GLI1), play a pivotal role in the stemness and drug resistance of lung cancer." (PMID 37149646, 2023). "The Kras/YY1/ZNF322/SHH transcriptional axis increases the expression levels of the SHH protein, leading to lung cancer malignant progression by inducing tumor angiogenesis." (PMID 35433472, 2022). "SHH is the dominant ligand that regulates lung development, adult lung airway homeostasis, and lung cancers." (PMID 32108165, 2020). "Studies have demonstrated that overexpression and activation of SHH signaling is involved in the development of many tumors, including lung cancer." (PMID 31783569, 2019). "Our lab recently studied upregulated signaling in lung cancer, investigating Gli1’s inverse correlation with E-cadherin; inhibition of the SHh pathway upregulates E-cadherin expression and suppresses lung cancer cell migration." (PMID 29416661, 2018). "Our study confirmed that aberrant activation of the SHH signal pathway conferred more proliferative and invasive phenotypes to human lung cancer cells." (PMID 28507311, 2017). "Although we have achieved significant results, there are still many issues that need to be explored in in-depth studies, such as the specificity in SBE-induced repression of SHH to enhance chemotherapeutic treatment of lung carcinoma drug resistance." (PMID 28507311, 2017). "Our study revealed that SHH signal pathways were aberrantly activated in lung cancer tissues and cells which conferred more proliferative and invasive phenotypes to human lung cancer cells and leading to adverse prognosis in patients." (PMID 28507311, 2017). "We also found that SBE significantly sensitized lung cancer cells to chemotherapeutic agent DDP via repressing SHH components in vitro and in vivo." (PMID 28507311, 2017). "We also found that SBE significantly sensitized lung cancer cell to chemotherapeutic agent DDP via repressing SHH components in vitro and in vivo." (PMID 28507311, 2017). "We also found SBE significantly sensitized lung cancer cell to chemotherapeutic agent DDP via repressing SHH components in vitro and in vivo." (PMID 28507311, 2017). "Meanwhile, reduction in transcription of Hedgehog cascade members as downstream targets of GLI1 back forwardly further attenuates the SHH signaling in lung cancer cells." (PMID 28507311, 2017).